TMEM158 (transmembrane protein 158)
Description:
Receptor for brain injury-derived neurotrophic peptide (BINP), a synthetic 13-mer peptide.
Synonyms: p40BBP; RIS1; BBP
Tractability: Antibody: UniProt predicts a signal peptide or a membrane-spanning region.
Gene: Protein-coding gene on chromosome 3 (45,224,466 to 45,226,287, reverse strand). Ensembl gene ENSG00000249992.
Subcellular location: Membrane
Gene Ontology:
Molecular function: peptide binding
Cellular component: membrane
Genetic constraint (gnomAD): Loss-of-function variants: 7 observed, 3.19 expected, observed/expected ratio (o/e) 2.19. That is too few expected variants to judge how well the gene tolerates losing a copy. Missense variants: 405 observed, 249.61 expected, observed/expected ratio (o/e) 1.62, 90% interval 1.5 to 1.76. Synonymous variants: 209 observed, 125.34 expected, observed/expected ratio (o/e) 1.67, 90% interval 1.49 to 1.87.
Homologues: Orthologues: chimpanzee TMEM158 (100% identical), macaque TMEM158 (95% identical), pig TMEM158 (91% identical), dog TMEM158 (86% identical), rat Tmem158 (86% identical), mouse Tmem158 (83% identical), tropical clawed frog tmem158 (47% identical).
Diseases named in the same sentence as TMEM158 in open-access papers:
TMEM158 is named in the same sentence as 41 diseases in open-access papers, as found by Europe PMC text mining. Sharing a sentence is not in itself a finding about the gene and the disease. The quoted sentences say what the papers report.
ovarian carcinoma (10 papers, 2009 to 2023). A malignant neoplasm originating from the surface ovarian epithelium. "Taken together, we found the overexpression of TMEM158 in ovarian cancer cells, which was associated with cancerous transformation." (PMID 26239324, 2015). "In a previous study, it has been evidenced that TMEM158 can promote tumor growth, such as regulating cell proliferation and invasion in ovarian cancer." (PMID 37404478, 2023). "TMEM158 oncogenic action was demonstrated in cell culture and mouse xenograft models derived from colon cancer, pancreatic cancer, ovarian cancer, glioblastoma, and triple-negative breast cancer." (PMID 36387246, 2022). "Previous studies have reported the expression and functions of TMEM158 in different tumors, including pancreatic cancer, ovarian cancer, and colorectal cancer." (PMID 34992215, 2022). "The involvement of TMEM158 in tumor growth has been studied in two ovarian cancer cell lines, HO-8910 and A2780." (PMID 30574087, 2018). "We then detected the protein and mRNA levels of TMEM158 in five ovarian cancer cell lines by Western blotting and real-time PCR, respectively." (PMID 26239324, 2015). "This study was aimed to elucidate the roles of TMEM158 in cell proliferation, adhesion and cell invasion of ovarian cancer cells." (PMID 26239324, 2015). "In the present study, analysis using high throughput RNA-sequencing data from TCGA demonstrated a higher expression of TMEM158 in ovarian cancer compared to normal tissues." (PMID 26239324, 2015). "The effects of TMEM158 knockdown in the proliferation, adhesion and invasion of ovarian cancer cells were assessed." (PMID 26239324, 2015). "To investigate the roles of TMEM158 in ovarian cancer, we determined its expression in ovarian cancer and normal tissues." (PMID 26239324, 2015). "Our data suggested that TMEM158 was involved in the regulation of ovarian cancer cell proliferation." (PMID 26239324, 2015). "Among all the 188 predefined ‘KEGG pathways’ gene sets, TGF-β signaling pathway and cell adhesion molecules was identified to be closely correlated with TMEM158 expression in the TCGA ovarian cancer dataset." (PMID 26239324, 2015). "To probe the TMEM158-associated pathways on an unbiased basis, we performed GSEA using high throughput RNA-sequencing data of the ovarian cancer cohort from TCGA." (PMID 26239324, 2015). "We then found that TMEM158 mRNA expression was elevated in 84 % (21/25) of tested ovarian cancer tissues by real-time PCR." (PMID 26239324, 2015). "To further investigate the functions of TMEM158 in ovarian cancer, we suppressed the expression of TMEM158 in two ovarian cells, HO-8910 and A2780 cells by RNA interference." (PMID 26239324, 2015). "The RNA-sequencing data of the ovarian cancer cohort from The Cancer Genome Atlas project (TCGA) and our real-time PCR data showed that TMEM158 was overexpressed in ovarian cancer." (PMID 26239324, 2015). "We then suppressed TMEM158 expression of ovarian cancer cells by RNA interference and examined the effects of TMEM158 knockdown on cancerous transformation of ovarian cancer cells." (PMID 26239324, 2015). "RT-PCR analyses of ovarian cancer samples validated gene expression profiles of TMEM158, GBE1 and HEG1 from a chromosome 3 transcriptome analysis and IGFBP4, PTRF and C1QTNF1 from a chromosome 17 transcriptome analysis." (PMID 19580657, 2009). "Silence of TMEM158 decreased ovarian cancer cell proliferation, cell adhesion, and cell invasion." (PMID 37970923, 2023). "TMEM158 is overexpressed in ovarian cancer and may promote the occurrence, proliferation, adhesion and invasion in ovarian cancer." (PMID 36254814, 2022). "In addition, TMEM158 is upregulated in ovarian cancer and significantly promotes the proliferation, invasion, cell adhesion, and tumorigenesis of ovarian cancer cells." (PMID 34992215, 2022).
ovarian carcinoma (continued). "In recent years, TMEM158 upregulation was reported in multiple human cancers, including colon cancers, thyroid cancers, triple-negative breast cancers, pancreatic cancers, laryngeal cancer, ovarian cancers, and glioblastomas." (PMID 36387246, 2022). "The silencing of TMEM158 in ovarian cancer cells promoted a G1-phase arrest, which may inhibit cell proliferation." (PMID 34960643, 2021). "TMEM158 is also overexpressed in ovarian cancer in 84% of the 25 tumor samples which were analyzed." (PMID 30574087, 2018). "Knockdown of TMEM158 by RNA interference in ovarian cancer cells significantly inhibited cell proliferation, which may be due to the increase of G1-phase arrest." (PMID 26239324, 2015). "Here, silencing of TMEM158 in ovarian cancer cells significantly promoted cell arrest in G1-phase, which may lead to the inhibition of cell proliferation." (PMID 26239324, 2015). "Whether TMEM158 can be used as a potential therapeutic target for ovarian cancer remains to be further investigated." (PMID 26239324, 2015). "Our data suggested that TMEM158 knockdown notably induced G1-phase cell cycle arrest in ovarian cancer cells, which may lead to the inhibition of cell proliferation." (PMID 26239324, 2015). "An overexpression of TMEM158 was found in 84 % (21/25) of tested ovarian cancer tissues." (PMID 26239324, 2015). "Our study provides original documentation for the overexpression of TMEM158 in ovarian cancer and it may be an effective therapeutic target for this disease." (PMID 26239324, 2015). "TMEM158 expression was significantly increased in ovarian cancer tissues as compared with the adjacent tissues, which indicated that TMEM158 may be an oncogene in ovarian cancer." (PMID 26239324, 2015). "Our data suggests that TMEM158 may work as an oncogene for ovarian cancer and that inhibition of TMEM158 may be a therapeutic strategy for ovarian cancer." (PMID 26239324, 2015). "All these results showed that TMEM158 may work as an oncogene in ovarian cancer." (PMID 30574087, 2018). "However, the expression and biological function of TMEM158 in ovarian cancer is still unclear." (PMID 26239324, 2015). "The exact pathway that TMEM158 may regulate in ovarian cancers remains unclear." (PMID 26239324, 2015). "In the presents study, TMEM158 knockdown significantly decreased the expression of TGF-β and BMP4, which indicated a relation between TMEM158 function and the regulation of TGF-β signaling in ovarian cancer cells." (PMID 26239324, 2015). "To further determine TMEM158 expression in ovarian cancer, we performed real-time PCR analysis on 25 pairs of ovarian cancer and their matched noncancerous tissue samples." (PMID 26239324, 2015). "We analyzed TMEM158 mRNA level in ovarian cancer tissues and adjacent no-tumorous tissues by real-time PCR." (PMID 26239324, 2015).
pancreatic cancer (10 papers, 2020 to 2024). "TMEM158 was shown to be abnormally upregulated in pancreatic cancer and to be associated with poor clinical outcomes through its activation of the PI3K/AKT pathway." (PMID 35711843, 2022). "TMEM158 was also found to be significantly overexpressed in pancreatic cancer and is associated with larger tumor size and poorer prognosis." (PMID 34992215, 2022). "Additionally, in pancreatic cancer, it has been reported that TMEM158 is significantly overexpressed and is associated with increased tumor size and poor prognosis." (PMID 37936608, 2023). "Studies of the mechanism have demonstrated that the activation of TGFβ1 and PI3K/AKT signals may be the aggressive cause of TMEM158 triggering pancreatic cancer." (PMID 35945754, 2022). "The empirical association between TMEM158 overexpression and pancreatic cancer cell progression via EMT stimulation indicates that TMEM158 can serve as a prognostic indicator for development of pancreatic tumor in terms of blood vessel invasion, TNM stage, and tumor size." (PMID 33928036, 2021). "Knockdown of TMEM158 inhibits the proliferation, migration, and invasion of pancreatic cancer cells." (PMID 34992215, 2022). "Blockade of TGFβ1 significantly reversed TMEM158 overexpression-induced pancreatic cancer cell metastasis and epithelial-mesenchymal transition." (PMID 35945754, 2022). "A recent finding on metastasis inducing function of TMEM158 through EMT activation also indicates this tumor promoter should be a target for pancreatic cancer therapy." (PMID 33928036, 2021). "TMEM158 gene expression is closely associated with the progression of ovarian and pancreatic cancers, but was not known to be involved in breast cancer." (PMID 35711843, 2022). "TMEM158 was significantly upregulated in pancreatic cancer samples." (PMID 35945754, 2022). "TMEM158 was able to stimulate increased PI3K/AKT signaling in pancreatic cancer cells." (PMID 35945754, 2022). "TMEM158 facilitates the progression of several carcinomas such as pancreatic cancer." (PMID 33352742, 2020). "Studies have revealed that TMEM158 can activate the TGF‐β1 and PI3K/AKT pathways, thereby promoting the invasion of pancreatic cancer." (PMID 39428922, 2024). "In addition, TMEM158 has an oncogenic role by increasing the expression of TGFβ1, vimentin, N-cadherin, and α-SMA that induce the EMT process and PI3K/AKT signaling that also regulates cancer cell proliferation, metastasis in pancreatic cancer." (PMID 37936608, 2023).
colorectal cancer (6 papers, 2017 to 2023). A primary or metastatic malignant neoplasm that affects the colon or rectum. "Studies show that TMEM158 frame-shift mutations are frequently detected in colorectal cancer and other studies show over expression of the gene in 15% of primary breast carcinomas." (PMID 28966727, 2017). "Moreover, loss of function of TMEM158 significantly decreased the proliferation and migration of colorectal cancer cells and inhibited multidrug resistance." (PMID 34992215, 2022). "In colorectal cancer, TMEM158 overexpression promotes cell proliferation and migration and inhibits apoptosis." (PMID 37936608, 2023). "TMEM158 was shown to be overexpressed in pancreatic, ovarian, and non-small cell lung cancers 29, and high expression of TMEM158 in colorectal cancer cells was found to promote drug resistance." (PMID 35711843, 2022). "Moreover, TMEM158 has been reported as the key regulator for tumorigenesis and drug resistance in colorectal cancer." (PMID 37064154, 2023).
glioma (6 papers, 2022 to 2023). A benign or malignant brain and spinal cord tumor that arises from glial cells (astrocytes, oligodendrocytes, ependymal cells). "Emerging research has reported that in glioma, high levels of expression of TMEM158 are associated with a poor prognosis and shorter survival time in patients, and its expression level is higher in the more advanced stages of glioblastoma." (PMID 37936608, 2023). "TMEM158 has been recently implicated in the carcinogenesis of multiple cancers, including gliomas, and more studies are needed to elucidate its exact mechanisms for possible future therapeutic targeting." (PMID 36425564, 2022). "Overall, these data suggest that TMEM158 is associated with glioma grades and is preferentially expressed in intratumoral of glioma tissues." (PMID 34992215, 2022). "We found that the underlying mechanism involves STAT3 activation mediating TMEM158-driven glioma progression." (PMID 34992215, 2022). "In addition, the effects of TMEM158 loss- and gain-of-function on the proliferation, migration, and invasion of glioma cells were assessed." (PMID 34992215, 2022). "For the first time, we associated TMEM158 with glioma cell growth, migration, and invasion via EMT and STAT3 signaling, suggesting that it may represent a useful therapeutic target for GBMs." (PMID 34992215, 2022). "TMEM158 is positively associated with glioma grade, IDH1 mutation status, and poor prognosis." (PMID 34992215, 2022). "To understand the molecular mechanisms underlying TMEM158-induced proliferation, migration, and invasion of glioma cells, we examined TMEM158-associated genes, which were enriched in the IL6-JAK-STAT3 signaling pathway as assessed using HALLMARK gene set enrichment analysis." (PMID 34992215, 2022). "The potential mechanisms involving STAT3 activation mediating TMEM158-driven glioma progression have also been identified, and the inhibitory effect of TMEM158 downregulation on glioma growth has been confirmed." (PMID 36755318, 2023). "First, we used a Transwell migration assay to determine the effect of TMEM158 on the migration ability of glioma cells." (PMID 34992215, 2022). "Cancer cells in patients with primary GBMs harbored significantly higher expression of TMEM158 than those in patients with WHO grade II or III gliomas." (PMID 34992215, 2022). "Here, we found that TMEM158 expression in human glioma cells in the tumor core was significantly higher than that in noncancerous cells at the tumor edge using bioinformatics analysis." (PMID 34992215, 2022). "In contrast, downregulating TMEM158 in glioma cells significantly increased the expression of E-Ca and decreased the expression of N-Ca, vimentin, and Snail." (PMID 34992215, 2022). "The results also revealed that overexpression of TMEM158 expression increased the invasion ability of glioma cells (p < 0.001)." (PMID 34992215, 2022). "Western blotting also showed that overexpression of STAT3 reduced the expression of E-Ca and increase the expression of N-Ca, vimentin, and Snail in glioma cells in response to TMEM158 knockdown." (PMID 34992215, 2022). "In this study, we first investigated the clinicopathological and biological characteristics of TMEM158 in gliomas." (PMID 34992215, 2022). "The CCK-8 assay showed that downregulating TMEM158 expression inhibited the proliferation of glioma cells, while overexpression of STAT3 rescued the reduced proliferation caused by TMEM158 knockdown." (PMID 34992215, 2022). "The results showed that the OS time of glioma patients with higher TMEM158 expression was shorter than that of glioma patients with lower TMEM158 expression in the TCGA RNA-seq database (p < 0.0001)." (PMID 34992215, 2022). "The results showed that glioma cell migration ability was enhanced when TMEM158 expression was upregulated (p < 0.001), while downregulating TMEM158 expression significantly decreased the motility of glioma cell (p < 0.001)." (PMID 34992215, 2022).
glioma (continued). "We also illustrated that TMEM158 mRNA expression was correlated with poor overall survival in glioma patients." (PMID 34992215, 2022). "Downregulating TMEM158 expression using shRNA significantly inhibited the invasion ability of glioma cells compared to the control group (p < 0.001)." (PMID 34992215, 2022). "In vivo results further confirmed the inhibitory effect of the TMEM158 downregulation on glioma growth." (PMID 34992215, 2022). "Further investigations revealed that TMEM158 enhanced glioma cell proliferation, migration, and invasion as well as the progression of epithelial mesenchymal transition (EMT) by activating STAT3 signaling in vitro as well as in a mouse model." (PMID 36425564, 2022). "Our investigation indicated that TMEM158 expression was positively related to WHO glioma grade and was more highly expressed in IDH1-WT gliomas than in IDH1-Mut gliomas for each WHO classification grade." (PMID 34992215, 2022). "In this study, we demonstrated that upregulating TMEM158 promotes the proliferation, migration, and invasion of glioma cells." (PMID 34992215, 2022). "First, we ranked the glioma samples according to their expression levels of TMEM158 in the TCGA database and then took the 25% of the samples at both ends as the high and low expression groups." (PMID 34992215, 2022). "To further investigate the potential mechanism of TMEM158 in gliomas, we conducted a series of bioinformatics analysis." (PMID 34992215, 2022). "Collectively, these findings further our understanding of the oncogenic function of TMEM158 in gliomas, which represents a potential therapeutic target, especially for GBMs." (PMID 34992215, 2022). "Mechanistically, we further confirmed that TMEM158 enhanced glioma cells proliferation, migration, and invasion as well as the progression of EMT by activating STAT3 signaling." (PMID 34992215, 2022). "Transmembrane protein 158 (TMEM158) has been shown to be significantly upregulated in primary glioblastoma (GBM) compared to WHO grade II or III gliomas based on multiple cancer database analyses." (PMID 36425564, 2022). "To further explore the expression pattern of TMEM158 in gliomas, we used IHC and RT-PCR to determine the relationship between the expression of TMEM158 in glioma tissue and glioma grade." (PMID 34992215, 2022). "TMEM158 can potentially enhance glioma cell motility by activating the EMT process." (PMID 37936608, 2023). "Likewise, the negative regulation of TMEM158 in glioma cells significantly increased the expression of E-Cadherin and decreased the expression of N-Cadherin, vimentin, and Snail." (PMID 37936608, 2023). "Furthermore, TMEM158 positively correlates with STAT3 signaling in glioma cells, and regulates the glioma cell proliferation, migration, invasion, and EMT process by activating STAT3 signaling." (PMID 37936608, 2023). "Furthermore, we demonstrated that silencing TMEM158 inhibited the proliferation of glioma cells and that TMEM158 overexpression promoted the migration and invasion of glioma cells by stimulating the EMT process." (PMID 34992215, 2022). "In conclusion, our work describes the molecular and clinical characterization of TMEM158 in glioma." (PMID 34992215, 2022). "Moreover, in the CGGA RNA-seq database (n = 693 and n = 325), glioma patients with higher TMEM158 expression had a worse prognosis than those with lower TMEM158 expression (p < 0.0001)." (PMID 34992215, 2022). "Downregulation of TMEM158 inhibited the colony formation efficiency of glioma cells (p < 0.001)." (PMID 34992215, 2022). "Although TMEM158 was initially proposed as a tumor suppressor gene upregulated during Ras-mediated senescence, recent studies suggest that TMEM158 has an oncogenic role in human cancers derived from the colon, pancreas, ovary, glioma, and breast." (PMID 36387246, 2022). "Therefore, we took advantage of clinical human glioma samples to detect the protein pattern of TMEM158 in a tissue microarray (TMA)." (PMID 34992215, 2022).